RN7SL864P (RNA, 7SL, cytoplasmic 864, pseudogene)
Gene: Miscellaneous RNA gene on chromosome 20 (14,223,041 to 14,223,325, forward strand). Ensembl gene ENSG00000239923.
Homologues: Orthologues: chimpanzee Metazoa_SRP (99% identical), dog Metazoa_SRP (63% identical), pig Metazoa_SRP (62% identical). Paralogues in human: RN7SL1 (73% identical), RN7SL3 (73% identical), RN7SL2 (73% identical), RN7SL357P (72% identical), RN7SL147P (72% identical), RN7SL448P (72% identical), RN7SL11P (71% identical), RN7SL18P (71% identical), RN7SL218P (71% identical), RN7SL126P (71% identical), RN7SL203P (71% identical), RN7SL278P (71% identical), and 699 more.